RNU7-182P (RNA, U7 small nuclear 182 pseudogene)
Gene: Small nuclear RNA gene on chromosome 2 (127,017,421 to 127,017,482, forward strand). Ensembl gene ENSG00000238788.
Homologues: Orthologues: chimpanzee U7 (98% identical), macaque U7 (77% identical). Paralogues in human: RNU7-48P (81% identical), RNU7-11P (77% identical), RNU7-59P (77% identical), RNU7-113P (76% identical), RNU7-160P (76% identical), RNU7-24P (76% identical), RNU7-26P (76% identical), RNU7-2P (76% identical), RNU7-30P (76% identical), RNU7-43P (76% identical), RNU7-79P (76% identical), RNU7-80P (76% identical), and 143 more.